INS (insulin)
Diseases named in the same sentence as INS in open-access papers (continued):
Sharing a sentence is not in itself a finding about the gene and the disease.
colon carcinoma (continued). "To substantiate the role of ACAT1 in colon cancer growth and metastasis promoted by insulin, we used ACAT1 siRNA to inhibit ACAT1 gene expression in HT-29 cells as described in Materials and Methods." (PMID 29793481, 2018). "To identify the effect of insulin on colon cancer cell growth, we tested the cell viability rate of the human colon cancer HT29 cells using CCK-8 assay in a 96-well format." (PMID 29793481, 2018). "Adiponectin is beneficial to inhibit colon tumor growth and improves insulin sensitivity by decreasing the serum insulin levels in mice fed with a HFD." (PMID 28170448, 2017). "It reduces circulating insulin, promotes weight loss and activates 5’ adenosine monophosphate-activated protein kinase (AMPK), thus inhibiting growth of colon cancer cells." (PMID 28060743, 2017). "MCF-7 cancer cells were pretreated with 40 μg/ml insulin (INS), while colon cancer cells with 100 μg/ml." (PMID 29371977, 2017). "Both insulin and sugars showed a pronounced effect in B(a)P high dose group, indicating their likely involvement in the progression and metastasis of colon cancer when B(a)P is taken in along with WD." (PMID 26959117, 2016). "A similar situation was observed for Akt1 phosphorylation in insulin-treated HCT116 colon cancer cells." (PMID 26945062, 2016). "Accelerative colon tumor growth was found in a mouse model of T2DM which got high level of insulin and IGF-1." (PMID 26901856, 2016). "This study was aimed to determine the mechanism of insulin/IGF-1 in colon cancer growth within a T2DM environment." (PMID 26901856, 2016). "Accelerative colon tumor growth was found in a mouse model of T2DM with db/db mice which got high level of endogenous insulin and IGF-1." (PMID 26901856, 2016). "We found that the combination of insulin and IGF-1 significantly promoted the growth and the cell cycle of murine colon cancer MC38 cells than single use of insulin or IGF-1 in vitro." (PMID 26901856, 2016). "The association between high levels of insulin and insulin-like growth factor-1 (IGF-1) and the risk of colon cancer has also been demonstrated." (PMID 26082438, 2015). "Insulin, IGF-1, and IGFBP-3 have also been linked with colon cancer in both in vitro and in vivo studies." (PMID 24732966, 2014). "Previous work from our laboratory have extensively used Transferrin and Insulin (jointly termed here as GF or growth factors) in combination to activate IGF-1R-mediated cell survival signaling in colon cancer cells." (PMID 24083380, 2013). "In vitro studies have shown that insulin promotes cell growth in colonic mucosa and in colon carcinoma cells." (PMID 22907422, 2012). "We found that Akt expression was up-regulated with high glucose and insulin in both cell lines, whereas PLCγ expression was enhanced in colon cancer cells only." (PMID 22554284, 2012). "In particular, increased fasting serum insulin concentrations, commonly found in DM2 patients, seem to increase the risk for breast and colon cancer." (PMID 22554284, 2012). "Comparable results were found in SW480 colon carcinoma cells with 1.9 days at 5.5 mM glucose vs 1.5 days at 11 mM glucose and 1.4 days at 11 mM plus 100 ng ml−1 insulin." (PMID 21179032, 2011). "Twenty-two patients (16%) who used oral antiglycaemic agents received a higher dose and 14 patients (33%) who used insulin received a higher dose after colon cancer diagnosis." (PMID 29090133, 2011). "One year after colon cancer diagnosis, one patient who formerly used an oral antiglycaemic agent, switched to insulin." (PMID 29090133, 2011). "Together with the elevated copy numbers of transcription factor E2F, these findings suggest increased proliferation rates as described for colon cancer after insulin stimulation." (PMID 21179032, 2011).
colon carcinoma (continued). "The significant health benefits of RS in improving digestive system health, regulating blood glucose levels, enhancing insulin sensitivity, aiding in weight control, increasing satiety, and preventing colon cancer will further consolidate its leading position in the health food market." (PMID 39942065, 2025). "Moreover, phloroglucinol was shown to inhibit cell growth by suppressing insulin signaling in human colon cancer HT-29 cells." (PMID 37997977, 2023). "It was demonstrated that Met could reverse insulin-induced oxaliplatin resistance via the AMPK/Erk pathway in human colon cancer cells." (PMID 37828612, 2023). "According to previous studies, insulin promotes colon cancer progression by increasing the expression of acyl-coenzyme A: cholesterol acyltransferase-1, and vascular cell adhesion molecule-1 in intestinal tumor endothelial cells, resulting in an inflammatory response that promotes malignancy." (PMID 36138391, 2022). "This suggests that the IGFs and insulin may positively regulate cell-cycle progression and thereby growth of colon cancer cells." (PMID 34290976, 2021). "In addition, it has been reported that insulin enhances anticancer functions of 5-FU in esophageal and colonic cancer cells." (PMID 34034636, 2021). "In addition, low-dose insulin supplementation was found to attenuate these processes in mice with advanced melanoma or colon carcinoma." (PMID 33362865, 2020). "Others have shown that insulin can increase colon tumor growth." (PMID 33346251, 2020). "Metformin also slows colon cancer growth in rodents in an insulin-dependent manner and may modestly reduce colon cancer incidence in diabetic humans." (PMID 31867105, 2019). "Consequently insulin-triggered cell proliferation and migration on colon cancer cells were inhibited." (PMID 29793481, 2018). "Exercise reduces visceral obesity and insulin among patients with colon cancer." (PMID 30332430, 2018). "In order to clarify the mechanism of unhealthy lifestyles lead to colon cancer, more and more studies found that lifestyle affect the regulation of insulin, and the insulin plays an important role in the initiation of cell growth and the proliferation of the colon cancer." (PMID 29793481, 2018). "We aim to test the effect of insulin on proliferation and migration of colon cancer cells." (PMID 29793481, 2018). "Insulin markedly promoted cell proliferation and migration in human colon cancer HT-29 cells." (PMID 29793481, 2018). "Our research conducted on breast and colon cancer cell lines demonstrated cytotoxic activity of thioglycoside A and thioglycoside B. Interestingly, this effect was significantly enhanced in the presence of insulin." (PMID 29371977, 2017). "The results revealed that insulin/IGF-1 inhibits colon cancer cells apoptosis in vitro." (PMID 26901856, 2016). "On the other hand, adiponectin which is negatively correlated with body fat mass, also plays a major role in energy balance and insulin sensitization, and may inhibit colon tumor cell proliferation." (PMID 23056418, 2012). "The presence of microRNA1 as a differentially regulated hub in MAM-treated animals is noteworthy because of its ability to regulate insulin signaling (especially the IGF-1 receptor), its association with colon cancer, and the key roles of ERK1 and microRNAs in tau phosphorylation and AD." (PMID 21731631, 2011). "This was followed by finding that vitamin D was necessary for normal insulin secretion, by an observational study of dietary vitamin D and calcium intakes and the risks of colon cancer in 1985, and of 25(OH)D concentrations in relation to the risks of colon cancer in 1989." (PMID 37189612, 2023). "Furthermore, it was reported in 2019, that insulin may be able to promote cell death and transport in colon cancer." (PMID 36983040, 2023).
colon carcinoma (continued). "Therefore, it can be speculated that CREB antagonizes the effect of insulin in colon cancer, reduces the activation and expression of CEBPA, and play a carcinogenic role." (PMID 35174151, 2022). "Similarly, insulin injection also promotes the progression of pancreatic cancer in Syrian hamsters, as well as the development and metastasis of breast and colon cancer in mice." (PMID 35244142, 2022). "In the present study, we found that blood insulin levels was associated with ACAT1 expression and clinic pathological characteristics, then we observed insulin improved cell proliferation and migration of colon cancer HT29 cells in a time and dose-dependent manner." (PMID 29793481, 2018). "However, few studies have been done on the mechanism of ACAT1 in insulin-related colon cancer." (PMID 29793481, 2018). "New insulin independent anti-diabetic therapy might be benefit to colon cancer with T2DM." (PMID 26901856, 2016). "Insulin may exert a proliferative effect on colonic tumor cells directly." (PMID 23781242, 2013). "Insulin and IGF-1 have significant implications in colon cancer development, as they activate the phosphatidylinositol 3-kinase (PI3K)/Akt signaling pathway, stimulating cell growth and cell cycle signaling." (PMID 37835359, 2023). "Recently, it was reported that insulin and EGF synergize in activating PD-L1 expression in colon cancer cells, an effect that involves the enhanced transport of PD-L1 to the cell surface." (PMID 34202040, 2021). "We aimed to evaluate in colon cancer cells a combination of six agents directed to block the tumor anabolism (orlistat + lonidamine + DON) and the host catabolism (growth hormone + insulin + indomethacin)." (PMID 33664364, 2021). "Dysfunction of PLCG1 is closely associated with inflammation, immune disorders, and cancer, and in vitro testing revealed that PLCG1 mediated high glucose levels and insulin-induced cell proliferation and migration in SW480 colon cancer cells." (PMID 32508884, 2020). "In human colon cancer cell line HT29, biglycan expression was induced by high sugar concentration, fatty acids, and insulin, and its contact co-culture with MSCs resulted in enhanced stemness and epithelial-mesenchymal transition phenotype." (PMID 32821344, 2020). "Insulin and IGF-1 are leading determinants of proliferation and apoptosis and therefore likely to influence colon cancer growth and tumorigenesis." (PMID 33346251, 2020). "We found that a combination of FU with insulin led to a significant decrease in viability in Caco-2 and SW480 colon cancer cells compared with FU alone." (PMID 31719636, 2019). "The other genes belong to metabolic pathways are GAPDH, INS, IGF1 which play significant role in proliferation and apoptosis in colon cancer." (PMID 30774816, 2018). "Previous study found that high levels of insulin conferred AKT signaling activation and resistance to oxaliplatin in colon cancer cell lines." (PMID 28969062, 2017). "Increased insulin and IGF-1 levels, together with decreased adiponectin levels, are also involved in the development of colon cancer." (PMID 29036907, 2017). "The correlation between insulin or IGF-1 and the risks of colon cancer in patients with T2DM is accepted widely." (PMID 26901856, 2016). "In this study, we investigated the effects and mechanisms of insulin and IGF-1 in colon cancer development in vitro and in vivo." (PMID 26901856, 2016). "In conclusion, our study suggests that the activation of ERK1/2 and JNK MAPK signaling by insulin and IGF-1, at least in part, is responsible for the development of colon cancer with T2DM." (PMID 26901856, 2016). "Excess energy consumption through diet may have resulted in elevated levels of insulin, triglycerides and fatty acids, which subsequently induced colonic epithelial cells to proliferate and also expose them to reactive oxygen intermediates, a setting ideal for colon cancer progression." (PMID 26959117, 2016).
colon carcinoma (continued). "Insulin and IGF-1 alone or together elevated proliferation and reduced apoptosis in colon cancer MC38 cells." (PMID 26901856, 2016). "We characterized insulin and IGF-1 receptor expression and the response to treatment with insulin, X10 and IGF-1 in the murine colon cancer cell line (MC38 cells) in vitro and in vivo." (PMID 24260289, 2013). "Here we show that the MC38 cell line, derived from a murine colon cancer, expresses IRs and IGF-1Rs and is insulin sensitive, as treatment with HI, X10 and IGF-1 results in activation of the PI3K and MAPK signalling pathways and increases proliferation." (PMID 24260289, 2013). "Moreover, higher dietary insulin load has been found to be correlated with increased cancer recurrence and poorer survival outcomes among individuals diagnosed with stage III colon cancer." (PMID 37468920, 2023). "Moreover, studies indicated that insulin and IGF-1 can enhance the proliferation of colon cancer cells and facilitate the growth of colon cancer allografts in obese mice." (PMID 37835359, 2023). "In this study, using syngeneic mouse colon cancer and melanoma models, we examined the effects of 6 common antidiabetic drugs on tumor inhibition of anti-PD1, including acarbose, sitagliptin, metformin, glimepiride, pioglitazone, and insulin." (PMID 36033393, 2022). "Thus, we suggest that the activation of ERK1/2 and JNK signaling by insulin and IGF-1, at least in part, is responsible for regulating the development and formation of colon cancer with T2DM." (PMID 26901856, 2016). "We speculated that insulin or IGF-1 got the same effects on MC38 cells, a mouse derived colon cancer cell line." (PMID 26901856, 2016). "In the present study, we observed that insulin and IGF-1, act as mitogens of colon cancer cells, activate the ERK1/2 and JNK MAPK signaling, resulting in cell cycle acceleration, cell growth and anti-apoptosis in colon cancer MC38 cells." (PMID 26901856, 2016). "In a previous study from our laboratory, lifetime consumption of SPI lowered: tumor incidence, body weight accretion and serum insulin and leptin levels in a non-obese, rat model of colon cancer." (PMID 23056418, 2012). "Studies among non-diabetic breast and colon cancer patients revealed that high levels of fasting insulin had an adverse prognostic effect on distant recurrence and death." (PMID 22526616, 2012). "Furthermore, C/EBP-β regulates energy balance, and promotes growth of colon cancer cells in part via activation of IGF-1, insulin, and leptin." (PMID 21048943, 2010). "Glimepiride, pioglitazone, and insulin are not recommended because they may reduce the colon tumor inhibitory effect of anti-PD1." (PMID 36033393, 2022). "Here, by employing syngeneic mouse colon cancer model and melanoma model, we studied the effects of 6 common antidiabetic drugs on anti-PD1 immune checkpoint inhibitor in tumor treatment, including acarbose, sitagliptin, metformin, glimepiride, pioglitazone, and insulin." (PMID 36033393, 2022). "High cholesterol ester content in lipid droplets is an important characteristic of tumors, and insulin can upregulate ACAT1 expression, an important enzyme that plays a role in the cholesterol esterification pathway, to promote the proliferation and migration of colon cancer cells (HT-29 cells)." (PMID 34485124, 2021). "Among the enriched pathways, RIG-I-like receptor signaling plays important roles in colon cancer; FoxO signaling pathway has been reported as therapeutic targets in cancer; autophagy was reported as a promising target for CRC; insulin signaling pathway could be a potential CRC therapy." (PMID 32680494, 2020). "Therefore, insulin could promote colon cancer progression by upregulation of ACAT1, which maybe is a potential therapeutic target for colon cancer." (PMID 29793481, 2018). "The increased insulin and IGF-1 may be responsible for the developing of colon cancer." (PMID 26901856, 2016).
colon carcinoma (continued). "The objective of the present study was to explore the effects of octreotide with or without insulin treatment, on Caco-2 and HT-29 human colon-cancer cell proliferation and to correlate their effects with the activation of telomerase reverse transcriptase (hTERT)." (PMID 25594044, 2014). "To analyze Akt/PLCγ expression, proliferation capacity, and cell migration we cultured different tumor cell lines (MDA-MB-468 breast and SW480 colon cancer cells) at physiological (5.5 mM, control) and diabetogenic (11 mM) glucose concentrations without and with 100 ng/ml insulin." (PMID 22554284, 2012). "The aim of this study was to evaluate the presence of somatostatin receptors on the colon cancer cell lines Caco-2 and HT-29, and to subsequently study the effects of the somatostatin analogue octreotide on cellular proliferation with or without the trophic effect of insulin." (PMID 25594044, 2014). "For instance, elevated levels of insulin and glucose may exert an important influence in the development or growth of epithelial malignant tumors of the colon, pancreas, and breast, and metformin may prevent incident colon cancer in non-diabetic subjects." (PMID 22448244, 2012). "Insulin and insulin-like growth factor (IGF)-1 have growth factor and antiapoptotic properties in a variety of cultured tumor and non-tumor cell types, including normal colon epithelium and colon cancer cells." (PMID 28060743, 2017).